PRKCD (protein kinase C delta)
Diseases named in the same sentence as PRKCD in open-access papers (continued):
Sharing a sentence is not in itself a finding about the gene and the disease.
cancer (continued). "Depending on our results, PRKCI, PRKCD, and PRKCZ associated-CNAs were driving their expressions in most cancers (except for PRKCI in DLBC, KICH, LAML, THCA, and THYM; PRKCD in GBM, HNSC, LAML, LGG, THYM, and UCS; and PRKCZ in ACC, GBM, KICH, LGG, THCA, THYM, and UCS)." (PMID 35174160, 2021). "In summary, among the prognostic genes we screened, the potential relationship amongBIRC5, HMOX1, and VEGFA in HCC prognosis had been reported previously, while VPS35might be a newly identified oncogene of HCC, and further, VPS26A and PRKCD were alsofound to have roles related to cancer." (PMID 33351066, 2021). "Whereas PRKCA, PRKCD, or PRKCG expression levels were negatively associated with the infiltration of immune cells in some cancers and positively correlated with immune infiltration in other cancers." (PMID 35174160, 2021). "In addition to epidermal renewal, IngMeb also activates Protein Kinase C -delta (PKC-δ) which has been found to induce apoptosis in cancer cell lines and induce upregulation of neutrophil mediators, (IL-8, TNF-α, ICAM-1, and E-selectin), resulting in massive neutrophil invasion to the skin." (PMID 27636884, 2016). "Annexin A3 (ANXA3) plays a critical role in promoting aggressive cancer and stem cell-like properties in HCC and is involved in mediating the activation of autophagy and attenuation of PKCd (PRKCD)/p38-dependent apoptotic signaling." (PMID 39272847, 2024). "Of note, an altered kinase signaling network involving EGFR, PDGFR, PAK1, PTK2 (FAK), PRKCD, and MAP2K2 appear to regulate the aberrant changes in the cancer cells and the TME accompanying recurrence." (PMID 35919862, 2022). "Otherwise, the correlations between PRKCA, PRKCD, PRKCE, and PRKCG expressions and the infiltration of the immune cells varied between cancer types." (PMID 35174160, 2021). "The results showed that mRNA levels of ATG10, IL18RAP, PRKCD, SLC11A1, and SPP1 differed between tumor tissues and normal tissues in most of the 33 cancer types." (PMID 34631695, 2021). "Western blot demonstrated that ATG10, PRKCD, and SPP1 were highly expressed in cancer tissues, while IL18RAP and SLC11A1 expression in cancer tissues was lower." (PMID 34631695, 2021). "For PRKCA, PRKCD, PRKCE, and PRKCG, the correlation between their expressions and HLAs enrichment scores were variable among different cancers." (PMID 35174160, 2021). "Our comprehensive gene expression analysis of all PKC isoforms revealed that three of the nine PKC coding genes (PRKCB, PRKCD and PRKCE) showed a down-regulation greater than two in the cancer tissue, while only one of the genes (PRKCG) was up-regulated." (PMID 26989024, 2016). "Interestingly, positively correlated loci represented cancer driver genes (MYC, PRKCD, RB1, CDK6), molecules involved in immune response (MALT1, PIK3CG), as well as cellular and hormonal signaling (HGF, PTPN13, IGF1, SMAD1, ESR1, CTGF)." (PMID 34368147, 2021). "For example, miR-21, miR-125b, miR-181a, miR-196a, and miR-148b suppress the expression of the apoptosis-related genes caspase-3, intercellular adhesion molecule-2 (ICAM-2), Protein Kinase C Delta (PRKCD), annexin A1 (ANXA1), or DNA methyltransferase 3b (DNMT3B) in a wide spectrum of cancers." (PMID 31174564, 2019). "Also, we predicted that PRKCA, PRKCD, and PRKCE might be involved in improving the response of many cancers to PD-L1 blocking-dependent immunotherapies, but their effect on HLA-dependent therapies may run in line with their effect on the TILs aggregation." (PMID 35174160, 2021).
tumor (37 papers, 2008 to 2026). "Analysis of The Cancer Genome Atlas (TCGA) RNA-seq data with TIMER2.025,26 showed that PRKCD expression was inversely correlated with tumor purity and positively associated with M1-like, anti-tumor macrophages in GBM." (PMID 41503214, 2026). "Recurrent fusions of PRKCB and PRKCD to membrane-associated proteins were identified in BFHs, one of the most common neoplasms in the skin." (PMID 33617877, 2021). "The protein encoded by PRKCD wasreported to be activated by diacylglycerol and acted as both a tumor suppressor anda positive regulator of cell cycle progression." (PMID 33351066, 2021). "A study on both cervical cancer lines and mouse tumor xenograft models found that higher miR‐181a levels were associated with resistance to radiotherapy, an effect mediated by the downregulation of the pro‐apoptotic PRKCD gene by miR‐181a." (PMID 41001946, 2025). "In addition, combined with clinicopathological parameters, we also found that the expression level of PRKCD was also positively associated with lymph node metastasis, distant metastasis, and tumor stage." (PMID 36816970, 2023). "This member has been linked to various molecular targets, including BCL2, PRKCD, and PI3K/AKT, making it a central player in chemoresistance, tumor growth, and metastasis." (PMID 41001946, 2025). "The results demonstrated that PHGDH knockdown significantly inhibited PDX tumor growth, reduced PRKCD mRNA and protein levels and decreased the expression of mitophagy-related molecules." (PMID 40681503, 2025). "Given that the STRING analysis revealed predicted interactions between tumor-associated CD318 and immune-related proteins such as CD6 and PRKCD, we further investigated the functional context of these associations using a Gene Ontology (GO) analysis." (PMID 40725832, 2025). "PRKCD (Protein Kinase C Delta) genes play a key role in growth inhibition, differentiation, apoptosis, and tumor suppression." (PMID 37328788, 2023). "Examination of the Mondor dataset showed that transcription of PRKCA and PRKCD were significantly upregulated in CRPC compared to HNPC tumours." (PMID 36550208, 2023). "Nine genes were upregulated in tumor tissues, while the PRKCD, RPS6KA1, CAT, and VEGFC genes were downregulated." (PMID 36254009, 2022). "We then examined the expression of 9 model genes in single cells and found that CDK1, AURKB, CCNA2, and CHEK1 are mainly expressed in CD4 cells, while PRKAA2, CDK5, and PRKCD are mainly expressed in tumor cells." (PMID 36120466, 2022). "The protein kinase C δ (PRKCD) is a member of the protein kinase C family of serine- and threonine-specific protein kinases and it is involving in manipulating tumor repopulation while receiving radiotherapy." (PMID 33682883, 2021). "The present study supports PRKCD to be a predictor for survival of CM patients, which is further supported by the high expression levels of PRKCD in CM tumor tissues than in the normal skin from the Oncomine gene expression database." (PMID 29088810, 2017). "The PRKCD expression levels in tumor tissue were higher than that in normal tissue in the Talantov study that included 45 CM tumor tissues and seven normal skins (P < 0.001)." (PMID 29088810, 2017). "Others genes in this cluster were targets of estrogen action (e.g. T-type calcium channel subunit; CACNA1G), capable of binding estrogen receptor alpha (FASN, SNCG), or involved in tumor suppression (PRKCD, RASL11A)." (PMID 18941504, 2008). "Moreover, the tumor-promoting effect of PHGDH was markedly reversed by shRNA- or sotrastaurin-mediated intervention targeting PRKCD." (PMID 40681503, 2025).
tumor (continued). "At the same time, KEGG and GSEA pathway analysis showed that PRKCD had a relationship with four core pathways related to tumor progression and metastasis, including the Notch signal pathway, cell adhesion, ECM receptor interaction, and cytokine receptor interaction." (PMID 36816970, 2023). "It is known that mitogen-activated protein kinases (MAP4K1 and MAP4K4) and the insulin resistance pathway (PRKCD and PRKAB1) may be associated with tumor progression through modulation of gene expression responsible for cell cycle, proliferation, and growth." (PMID 35453789, 2022). "Moreover, in vitro experiments demonstrated that PRKCD could act as a molecular bridge between tumor cells and platelets, which could either participate in regulating tumor malignant phenotype or mediating platelet activation." (PMID 36463115, 2022). "According to prior surveys, MPs can downregulate specific genes in tumor cells, such as BCAS3, PHF19, and PRKCD, whose expression has been suppressed by microplastics in previous studies." (PMID 41378310, 2025). "And in CRC tumor tissues(TCGA-COAD and TCGA-READ), the expression of PRKCD was also significantly higher than that in normal tissues." (PMID 36816970, 2023). "Cell trajectories showed that the expression of PRKCD, PRKAA2, CDK5, and CDK1 genes increased from hepatocytes to tumor cells." (PMID 36120466, 2022). "We found that PRKCD, PRKAA2, CDK5, and CDK1 genes were increased in the progression from hepatocytes to tumor cells." (PMID 36120466, 2022). "To dissect the dynamic changes of both kinases and phosphoproteins in PDAC, we performed kinase–substrate enrichment analysis (KSEA), and four kinases (HIPK2, ROCK1, PRKCD, MAPKAPK2) were identified as tumor-specific activated." (PMID 36434634, 2022). "In brief, this work reveals a novel platelet-related risk signature for prognostic evaluation of HCC patients and confirms that PRKCD is a key messenger in HCC cell-platelet interaction and plays a crucial role in mediating platelet-induced tumor progression." (PMID 36463115, 2022). "Several potential substrates for PTPN14, including β-catenin, p130Cas, RIN1 and PRKCD, and YAP, are all related to tumor progression and metastasis." (PMID 35135548, 2022). "GEO datasets validated that the 6 genes (SHC1, FKBP4, NRAS, PRKCD, KRAS, ADCY9) had different expression between tumor tissues and adjacent normal tissues in LUAD, and 3 genes (FKBP4, KRAS, ADCY9) were related to the prognosis of LUAD." (PMID 33936178, 2021). "Among them, SHC1, FKBP4, NRAS, KRAS had higher expression, and PRKCD, ADCY9 had lower expression in LUAD tumor tissues compared with normal tissue." (PMID 33936178, 2021). "Compared with the normal samples, ATG10, PRKCD, and SPP1 were highly expressed in the tumor samples." (PMID 34631695, 2021). "By analyzing the correlation between five genes and tumor microenvironment, we found that SPP1, PRKCD, and SLC11A1 were highly positively correlated with macrophages." (PMID 34631695, 2021). "PRKCD and PRKD3 belong to protein kinase C (PKC) family, whose members also serve as major receptors for phorbol esters, a class of tumor promoters." (PMID 25961669, 2015). "In brief, this work reveals a novel platelet-related risk signature for prognostic evaluation of HCC patients and confirms that PRKCD is a key messenger in the interaction between HCC cells and platelets, which plays a crucial role in mediating platelet-induced tumor progression." (PMID 36463115, 2022). "Levels of PRKCD and SPP1 also varied among different clinical stages and tumor grades." (PMID 34631695, 2021).
tumor (continued). "Additionally, several non-receptor kinases and phosphatases such as PRKCD, PPP1R11, CRKL and PTPRA4 were identified for the first time as implicated in the crosstalk between CAFs and tumor epithelial cells." (PMID 29946230, 2018). "PRKCD appears to have dual functions in carcinogenesis not specific for a particular tumor type." (PMID 29088810, 2017).
myopathy (2 papers, 2024 to 2025). A disease of the muscle in which the muscle fibers do not function properly. "The top five up-regulated genes in general myopathy are MGST1, AOX1, FASN, PRKCD, and CHRNA1, which have been rarely reported in previous myopathy studies." (PMID 38600180, 2024). "We selected four up-regulated genes for general myopathy (MGST1, AOX1, FASN, PRKCD), CD163 for IBM, and CYP4B1 for titinopathy, aiming to validate their actual expression in our local muscles." (PMID 38600180, 2024). "The genes featured for general myopathy indeed showed relatively higher expression trend in the myopathy muscles: MGST1 (RQ 10.34/2.09, p = 0.02), AOX1 (RQ 4.53/2.41, p = 0.42), FASN (RQ 3.75/1.75, p = 0.10), PRKCD (RQ 2.10/1.23, p = 0.19)." (PMID 38600180, 2024).
neurodegenerative disease (1 paper, 2022). A disorder of the central nervous system characterized by gradual and progressive loss of neural tissue and neurologic function. "Mn has been demonstrated to produce apoptosis in dopamine neurons in a caspase-3-dependent manner by stimulating protein kinase C delta; this protein kinase C delta has been associated with neurodegenerative diseases such as PD." (PMID 36552676, 2022).
PRKCD also shares sentences with these, for which no sentence is quoted: colon carcinoma (2 papers); infection (2); ischemic stroke (2); mesothelioma (2); pituitary adenoma (2); prediabetes (2); adrenocortical carcinoma (1); attention deficit-hyperactivity disorder (1); Barth syndrome (1); Cerebral ischemia (1); chondrosarcoma (1); chronic hepatitis (1); colitis (1); Crohn disease (1); diffuse large B-cell lymphoma (1); escherichia coli infection (1); esophageal squamous cell carcinoma (1); fibrolamellar carcinoma (1); fungal infections (1); gallbladder cancer (1); genetic disorders (1); glioma (1); Hepatic fibrosis (1); Hepatic steatosis (1); Huntington disease (1); immunodeficiencies (1); lung adenocarcinoma (1); lymphoma (1); mastitis (1); muscular disease (1).
A further 16 diseases each share a sentence with PRKCD in 1 paper.